MUC1 (mucin 1, cell surface associated)
Diseases named in the same sentence as MUC1 in open-access papers (continued):
Sharing a sentence is not in itself a finding about the gene and the disease.
cancer (continued). "Our findings support the anticancer vaccine activity by which HDEA@EVAT expedites the interaction between DCs and CD8+ T-cells by inducing DC-targeted maturation and by presenting the cancer-associated peptide MUC1." (PMID 30691225, 2019). "For example, the high molecular weight tumor-associated glycoprotein, MUC1 (CD227), has been used as a target for cancer immunotherapy studies in both mice and in human clinical trials." (PMID 31430935, 2019). "It is believed that the attachment density and the structure of O-glycans of MUC1 expressed by carcinoma cells are distinct from those of normal epithelia-associated MUC1." (PMID 31719620, 2019). "In accordance, STAT3 activation via LMP1 induces the expression of mucin 1 cell surface-associated (MUC1), a glycoprotein involved in the early steps of cancer cell detachment." (PMID 29543893, 2018). "Increases in the UDP-GlcNAc levels can also lead to an increase in transcription of sialyltransferases and the addition of sialic acid to proteins, such as MUC1, is associated with metastasis in cancer." (PMID 29912148, 2018). "Survivin, a member of the inhibitor of apoptosis family of proteins, and mucin 1 (MUC1), a cell-surface glycoprotein, are TAAs that are expressed by a broad range of human cancers that cause significant morbidity and mortality worldwide." (PMID 29415891, 2018). "Recently, cancer-associated Tn glycoform of MUC1, a neoantigen expressed in a variety of cancers, was identified as a promising target that can be recognized by CAR-T-cells." (PMID 28116322, 2017). "Because this cancer-associated Tn glycoform of MUC1 is an abnormal self-antigen, with expression restricted to only various cancers and not in normal tissues, it has great potential to be tested in future clinical trials." (PMID 28434147, 2017). "TG4010 is a therapeutic cancer vaccine based on a modified vaccinia Ankara strain (MVA) encoding for the full-length cancer antigen Mucin 1 (MUC1) and human IL-2." (PMID 28923084, 2017). "We have used the sensitive force probe optical tweezers to quantify the interactions occurring between MGL lectins and MUC1 carrying the cancer-associated glycan antigens mucins Tn and STn." (PMID 28414807, 2017). "Recent studies indicate that MUC1 causes transcriptional alterations that result in metabolic reprogramming in cancer cells." (PMID 28464016, 2017). "This includes a frequent T112P mutation in MUC1 that is seen in half of the pancreatic MUC1 mutations, as well as being present in other cancers." (PMID 28978023, 2017). "MUC1 has long been associated with BC and has been prioritized as one of the most important cancer antigens." (PMID 28680538, 2017). "CARs targeting the cancer-associated Tn-glycoform of the membrane mucin MUC1 were constructed and demonstrated that they had target-specific cytotoxicity in mice with leukemia and pancreatic cancer." (PMID 28434147, 2017). "In this paper we quantify and compare the strength of the molecular interaction between the two cancer associated antigens MUC1(Tn) and MUC1(STn) and the lectin MGL by use of OT." (PMID 28414807, 2017). "One recent study reported cancer-associated autoantibodies against a set of aberrantly glycosylated glycopeptides derived from mucin MUC1 and MUC4 in sera of CRC patients." (PMID 27705923, 2017). "We have used OT to provide further evidence of the interactions occurring between MGL lectins and the cancer-associated antigens mucins MUC1(Tn) and MUC1(STn)." (PMID 28414807, 2017). "The overexpression of MUC1 has been noted in cancer cells with regard to features associated biochemically and functionally." (PMID 29250208, 2017). "This is attributed to molecular mimicry in which microorganisms causing these infections have certain antigens (such as MUC1) that induce a lifelong immunity, which then recognizes the same antigen on cancer cells." (PMID 28534024, 2017).
cancer (continued). "The diagnostic sensitivity of serum WFA-sialylated MUC1 in stage I and II carcinomas was excellent, and was highly superior to that of CA19-9 and CEA." (PMID 27358229, 2017). "Of particular interest, the levels of the multidrug resistance-associated protein-1 (MRP1) encoded by the ABCC1 gene were significantly higher in the MUC1-high cancer cells." (PMID 27029067, 2016). "Tyrosine kinase activity is well known to promote cancer progression, which is likely a major attribute to the specific association of the MUC1 network and CRPC." (PMID 27825118, 2016). "Galectin-4 promotes cancer cell adhesion to vascular endothelial cells by interaction with the Thomsen-Friedenreich (TF) disaccharide on cancer-associated MUC1." (PMID 27017379, 2016). "There is accumulating evidence demonstrating an association of MUC1 upregulation with cancer progression, including PC." (PMID 27825118, 2016). "In contrast to its polarized localization on the apical surface of epithelial cells in normal epithelium, cancer-associated MUC1 loses its apical localization and is expressed on the entire cell surface." (PMID 27066458, 2016). "The deficient extension of its O-glycan side chains leads to the production of underglycosylated forms of MUC1 where the exposure of immunogenic epitopes can trigger the immune response and cancer-associated inflammation." (PMID 27409642, 2016). "Overexpression of the genes linked to mucin production, specifically MUC1, is associated with many types of cancer." (PMID 27885342, 2016). "MUC1 has been implicated in cancer progression in many model systems and has been shown to modulate cancer cell adhesion and migration, evasion of immune surveillance, and cancer cell signaling." (PMID 27846218, 2016). "As previously shown for galectin-3, this interaction causes MUC1 cell surface polarization, thus leading to exposure of underlying adhesion molecules that promote cancer-endothelium adhesion, which indicates a metastasis-promoting effect." (PMID 27017379, 2016). "Cancer-associated MUC1 also carries other truncated oligosaccharides such as Tn and sialyl-Tn antigens." (PMID 27066458, 2016). "Cancer-associated MUC1 is characterized by the presence of specifically altered carbohydrate side chains in its extracellular tandem-repeat domain due to fundamental changes in glycosyltransferase activity and expression." (PMID 25670999, 2015). "In contrast, MUC1 rs4072037 was shown to decrease the cancer risk (CT vs. TT: adjusted OR = 0.77, 95% CI = 0.60–0.98)." (PMID 25658482, 2015). "The tumor-associated glycoprotein MUC1 represents a well-established target for cancer immunotherapy and has been used for the construction of various synthetic vaccine candidates." (PMID 25670999, 2015). "Although the relationship between MUC1 and cancer stem cells remains unexplored, a considerable number of recent studies have revealed that MUC1 is associated with cancer stem cells." (PMID 26016502, 2015). "This is potentially important because numerous studies have demonstrated that the C-terminus of MUC1 has oncogenic potential, associates with poor prognosis and drug resistance, and induces “stemness” features in a range of human carcinomas." (PMID 26374823, 2015). "When studies were segregated based on source of control, MUC1 rs4072037 polymorphism was found to be associated with decreased cancer risk, the results were equal to subgroup analysis of cancer subtypes." (PMID 24755768, 2014). "When evaluating the association between the MUC1 rs4072037 polymorphism and the susceptibility to cancer, we found that there was significant heterogeneity for the allelic comparison (G vs A: Pheterogeneity = 0.01, I2 = 63%)." (PMID 24755768, 2014). "The results of our meta-analysis indicated that the G allele of MUC1 rs4072037 variation was significantly associated with decreased risk of cancer." (PMID 24755768, 2014).
cancer (continued). "Further stratification analysis by ethnicity, the results showed that MUC1 rs4072037 polymorphism was significantly linked to cancer risk." (PMID 24755768, 2014). "The aim of this study is to provide a precise quantification for the association between MUC1 rs4072037 variation and the risk of cancer." (PMID 24755768, 2014). "Antibodies that form part of the components of IVD reagents used to detect the cancer marker CA15-3 recognize a peptide moiety that includes an O-glycosylation site that is exposed by decreased O-glycosylation of MUC1 that is associated with breast cancer." (PMID 25336120, 2014). "In the present study, we firstly analyzed the association of MUC1 rs4072037 of cancer in the overall cancer types." (PMID 24755768, 2014). "Overexpression of MUC1 as found in human carcinomas is associated with accumulation of MUC1-C in cytoplasm and targeting of MUC1-C to the nucleus." (PMID 25410981, 2014). "Although numerous diagnostic reagents and cancer vaccines have been designed based on abnormally glycosylated MUC1 sequences, the glycan and peptide sequences responsible for immune responses in vivo are poorly understood." (PMID 23023583, 2012). "The cancer associated glycoprotein MUC1 is an important model molecule in cancer immunotherapy and is aberrantly glycosylated in most adenocarcinomas." (PMID 23189185, 2012). "Another platform utilizes an identified cancer-specific immunodominant glycopeptide epitope in MUC1, a heavily glycosylated mucin known to be associated to several cancer types including breast and ovarian cancer." (PMID 24957768, 2012). "Targeting cancer associated glycopeptide epitopes in MUC1 such as GalNAc-MUC1 would be favorable, but biosynthesis of MUC1 glycopeptide epitopes expressed by tumors has been hampered by lack of relevant technologies and high costs." (PMID 23189185, 2012). "As such, MUC1 represents a useful diagnostic and prognostic marker in cancer patients, and MUC1 vaccines targeting the ectodomain are currently being studied in ongoing clinical trials." (PMID 22586492, 2012). "Expression of EGFR, Src, integrin αvβ5, and MUC1 are associated with the invasive and metastatic potential of various human cancers." (PMID 22586492, 2012). "Genes associated with the metastatic ability of cancer stem cells, especially Muc-1, MMP9 and Myc, were strongly reduced by CD44 knockdown." (PMID 22152097, 2011). "The ICAM-1 binding site on MUC1 lies within the peptide core, exposed in the cancer-associated, aberrantly glycosylated mucin, and MUC1 binds to domain 1 of ICAM-1." (PMID 24212946, 2011). "High levels of MUC1 expression, particularly in the cytoplasm, are associated with a poor prognosis in a variety of carcinomas." (PMID 24212946, 2011). "Despite the fact that high-titered MUC-1-specific autoantibodies are frequently found in cancer patients, their use as single diagnostic parameters is hampered by the circumstance that they can be detected at an almost similar frequency in healthy donors." (PMID 21234352, 2010). "The increased expression of MUC1 and the increased occurrence of TF antigen are both associated, independently, with high metastatic potential of the cancer cells and poor prognosis of the patients." (PMID 20565834, 2010). "Aberrant and incomplete glycosylation of MUC-1 is often associated with various epithelial cancer cells (breast, ovary, colon, pancreas lungs and prostate)." (PMID 27713328, 2010). "This study shows that the presence of galectin-3 at pathologically-relevant circulating galectin-3 concentrations increases cancer cell homotypic aggregation by interaction with cancer-associated MUC1 that expresses the TF disaccharide." (PMID 20565834, 2010). "CD227 (MUC1), a membrane-associated mucin that displays altered O-glycosylation patterns in carcinomas, presents as an independent prognostic factor of CRC." (PMID 21339979, 2010). "During the course of various cancer-related studies, several variant MUC1 transcripts were reported." (PMID 19238635, 2008).
cancer (continued). "Differential expression of MUC1 variants, including MUC1/1 and MUC1/2, has been noted previously in ovarian and breast cancers." (PMID 19578514, 2008). "MUC1 is a highly polymorphic membrane-associated mucin that is often aberrantly expressed in cancer." (PMID 19238635, 2008). "Through multivariate Principal Component Analysis, in HNSCC, a positive correlation was found between immunohistochemistry MUC1 detection and Cancer Associated Serum Assay levels (Kendall τ = 0.275, p = 0.005)." (PMID 17064405, 2006). "Many of the oncogenic effects of MUC1 stem from its cytoplasmic tail, which binds to several proteins implicated in cancer, including c-Src and the epidermal growth factor receptor (EGFR) family." (PMID 16846534, 2006). "Overexpression of MUC1 and the expression of aberrant forms of MUC1, typified by the loss of apical distribution, have been reported in many carcinomas, in particular breast and ovarian." (PMID 16265351, 2005). "Previous studies have reported that MUC1 was developmentally regulated and aberrantly expressed by carcinomas, and a high level of MUC1 mRNA expression in adenocarcinoma has been associated with poor prognosis." (PMID 16117833, 2005). "Inappropriate levels of MUC1 cause a disruption in the epithelial cell polarity and change the downstream signals through the cytoplasmic domain of MUC1, leading to an enhanced malignant potential of cancer." (PMID 40655139, 2025). "It was revealed that polymorphism in the MUC1 tandem repeats influences the expression of specific cancer sugar antigens in GC cells and may therefore allow the identification of subgroups of patients that develop more aggressive tumors expressing T antigen." (PMID 41154387, 2025). "MUC1 is a glycoprotein on the surface of all epithelial cells; its abnormal expression is associated with a cancerous phenotype, making it an ideal target for developing a cancer vaccine." (PMID 40547025, 2025). "Additionally, the subcellular distribution of MUC1 is related to glycosylation status, and loss of normal apical polarity in malignant cells, reinforces its potential importance in cancer progression." (PMID 41332218, 2025). "Current studies have found a profound association of MUC1 overexpression in numerous cancer types." (PMID 40699805, 2025). "MUC1 is generally overexpressed in cancer cells, which could also be associated with protection against NK cells, regardless of the expression levels of NK-associated receptors." (PMID 40710292, 2025). "We analyzed whether putative AR subpopulations display different MUC1 patterns as compared with other carcinoma cells and whether there is any association with cell proliferation and apoptosis rates." (PMID 41332218, 2025). "Thus, MUC1 presented unique properties in cancer cells, including the aberrant glycosylation pattern, loss of polarity and overexpression, making it an attractive TAA target." (PMID 39664199, 2024). "Additionally, ST6GALNAC1 and MUC1 collectively participate in the expression of tumor-associated glycan antigen STn in cancer cells, potentially affecting dendritic cell maturation and thus influencing immune responses." (PMID 38997719, 2024). "Predictive biomarkers of MUC1 vaccine response may lead to more effective vaccines tailored to individuals with high risk for cancer but with varying immune fitness." (PMID 39450169, 2024). "The stimulated expression of MUC1 on the cell surface, due to increased levels of estrogen and progesterone, affects the phenotypic identity and predisposition to the invasive growth and metastasis of cancer cells." (PMID 39456554, 2024). "Ovarian and other cancers are associated with increased expression of MUC1." (PMID 37608907, 2023).
cancer (continued). "T antigen (Galβ1-3GalNAcα-Ser/Thr; CD176; the Thomsen-Friedenreich (TF) antigen), which is covered by more expanded glycosylation and sialylation in normal epithelium, found in ~90% of all human cancers, is an intermediate structure in the biosynthesis of O-complex O-linked oligosaccharides on MUC1." (PMID 37345016, 2023). "Finally, we analyzed the correlation between CA15-3—a circulating biomarker derived from MUC1—and different serum parameters associated with cancer-related systemic inflammation." (PMID 36902242, 2023). "The studies show that cancer-associated MUC1 mucin is one of the most desirable, natural ligands for galectin-3, and that such interactions are mediated mostly via the binding of Gal-3 to the T carbohydrate, a prominent tumor-associated antigen on MUC1 mucin." (PMID 37345016, 2023). "Thus, many researchers consider tandem repeats of tumor‐associated MUC1 (tMUC1) as an ideal cancer antigen." (PMID 34694686, 2022). "In addition, according to their further research, the anticancer-associated human MUC1 preventive vaccination specifically induced humoral immunity postponed cancer development, and boosted the BRCA-bearing mouse survival." (PMID 35883508, 2022). "Additionally, MUC1-associated antibody production and cellular immune responses have been shown to exert a positive effect on cancer patient outcomes." (PMID 35351156, 2022). "In addition, cancer associated form of MUC1 is unique in that it is underglycosylated, and therefore, its core peptides have become accessible for interaction with these receptors." (PMID 34694686, 2022). "In contrast to the association of pTyr705-Stat3 with an AR+/ERβ+/MUC1+ epithelial phenotype, pSer727-Stat3 is associated with a basal cell phenotype, again analogous to the mesenchymal phenotype induced by pSer727-Stat3 in other cancers." (PMID 36017196, 2022). "Furthermore, in addition to transformation and loss of polarity in cancer cells, MUC1 is aberrantly overexpressed on the entire borders of greater than 90% of BC cells." (PMID 35248049, 2022). "Among these antigens, mucin 1 (MUC1) represents one of the most promising targets for the development of protective vaccines, as the overexpression of this gene is associated with colon, pancreatic, breast, and various other carcinomas." (PMID 35814435, 2022). "Interestingly, in our further exploration, we found that the MUC1 promoter region had two reverse Y-box sequences, which was the first attempt to link these two classic cancer markers into one combination diagnostic approach." (PMID 34976785, 2021). "MUC1 was associated with the increased proliferation and metastatic potential of cancer cells." (PMID 33922995, 2021). "Thus, the exact mechanisms of MUC1 endocytosis in relation to ADCC need to be further studied to be able to allow anti-MUC1 antibodies to bind optimally to cancer-associated MUC1 epitopes." (PMID 34070311, 2021). "The loss of MUC1 reduces the activity of intracellular anti-apoptotic pathways, increases sensitivity to reactive oxygen species (ROS), and potentially exposes the cancer cell to immune recognition." (PMID 30929156, 2020). "Moreover, there was a trend that CD68+CXCL5+ macrophages in the stroma around the edges of the cancer nests to be associated with MUC1-ST expression." (PMID 33149188, 2020). "In addition, MUC1-derived glycopeptides associated with cancer are amongst the array of glycoepitopes used in vaccines explored in clinical trials 137; however, with yet limited success." (PMID 32308758, 2020). "Also, when mucin MUC1 is expressed on cancer cells and is decorated with multiple short, sialylated O-linked glycans (MUC1-ST), which will induce TAM to express M2-like phenotype." (PMID 33365025, 2020). "The MUC1 oncoprotein is known to be linked with different types of cancer." (PMID 34803270, 2020). "Moreover, MUC1 is reported to be associated with the cancer invasiveness and metastasis, neo-angiogenesis, drug resistance, and poor prognosis." (PMID 33106534, 2020).